EPHB2 (EPH receptor B2)
Diseases named in the same sentence as EPHB2 in open-access papers (continued):
Sharing a sentence is not in itself a finding about the gene and the disease.
colorectal tumors (7 papers, 2006 to 2024). "Crossing ApcMin/+ mice with animals expressing a dominant negative form of EphB2 resulted in a loss of EphB activity that accelerated colorectal tumor progression." (PMID 38391938, 2024). "Loss of EPHB2 expression in colorectal tumors has also been associated with worse prognosis." (PMID 18682749, 2008). "Based on the growing evidence of the role of EPHB2 in CRC, we hypothesized that EPHB2 germline alterations may predispose to colorectal tumors." (PMID 16740153, 2006). "Conversely there are clinical data showing that EphB3 and EphB2 expression is significantly reduced in advanced and spread colorectal tumors, suggesting a tumor suppressive function for these receptors." (PMID 32316101, 2020). "Expression of ERBB3 and intestinal stem cell markers (LGR5, EPHB2, CD44s and CD44v6) was assessed by qRT-PCR in primary colorectal tumours (stages 0 to IV) and matched normal tissues from 53 patients." (PMID 26367378, 2015). "In our recent study, we found even more profound reduction in EPHB2 levels in colorectal tumors with serrated histology when compared to conventional CRC." (PMID 16740153, 2006). "This, together with the growing evidence of the role of EPHB2 in CRC tumorigenesis, prompted us to further investigate the role of EPHB2 in colorectal tumor predisposition." (PMID 16740153, 2006). "The rarity of germline EPHB2 mutations supports a more significant role for EPHB2 in colorectal tumor progression rather than in tumor initiation." (PMID 18682749, 2008). "We detected novel germline EPHB2 alterations in patients with colorectal tumors." (PMID 16740153, 2006). "We report here the first EPHB2 germline alterations in patients with colorectal tumors." (PMID 16740153, 2006). "In addition, in the cell lines that contained a detectable and robust ERBB3 cell population (LIM1215 and LIM1899), EPHB2 and ERBB3 marked distinct cell populations, as observed in our study in human colorectal tumours." (PMID 26367378, 2015). "Furthermore, a pattern of inactivation similar to EPHB2 has been observed for EPHB4 and EPHB3 in colorectal tumors and/or cell lines, respectively." (PMID 16740153, 2006). "In addition, colorectal tumours that did not contain any MUC2+ cells still had an EPHB2-/ERBB3+ cell population (data not shown)." (PMID 26367378, 2015).
ependymoma (7 papers, 2014 to 2025). A WHO grade II, slow growing tumor of children and young adults, usually located intraventricularly. "Although the exact mechanism underlying EphB2-mediated ependymoma development remains unclear, the response of untransformed and transformed eNSCs to ligand mediated ephrin signaling may shed light on this mystery." (PMID 25801123, 2015). "For example, the transcriptome of a subgroup of supratentorial ependymoma with amplified EPHB2 and CDKN2A loss (subgroup D) closely matched that of embryonic cerebral Cdkn2a−/− NSCs, whereas spinal ependymomas resembled adult wild-type NSCs from the spinal cord." (PMID 25008045, 2014). "Genetic and transcriptome analyses revealed that EphB2 is amplified or upregulated by EPN-ZFTA in supratentorial ependymoma, and EphB2 is a signature tyrosine kinase of the BL2 subtype in TNBC." (PMID 40943224, 2025). "The multikinase inhibitor dasatinib suppressed the growth of ependymoma through inhibition of EphB2 signaling." (PMID 40943224, 2025). "Since EphB2 is expressed in eNSCs, it is plausible that the increased EphB2 expression observed in ependymoma is the result of the cells inability to shutoff receptor expression." (PMID 25801123, 2015). "Recently, a comprehensive in vitro and in vivo high-throughput screen used a mouse model of the Ephb2-amplified ependymoma subgroup to identify potential therapies with predicted toxicity against normal NSCs." (PMID 25008045, 2014). "Recent studies confirmed EPHB2 as an ependymoma oncogene, suggesting that the dysregulation of receptor expression may contribute to tumorigenesis." (PMID 38612645, 2024). "A recent study demonstrated that the oncogene EPH receptor B2 (EPHB2) could induce an ependymoma by converting an RGC in the forebrain into a CSC." (PMID 34203272, 2021). "Ephrin receptor B2 (EPHB2)-driven ST ependymoma models—also highly expressed in ST-EPN-RELA tumors—have pinpointed 5-fluorouracil treatment as a potential cytotoxic therapy with efficacy in murine models and is currently being evaluated in early phase ependymoma clinical trials." (PMID 27858204, 2017). "The role of EphB2 as an ependymoma oncogene is demonstrated clearly in our implantation mouse model of the disease; however, the requirement and potential impact of receptor activation on this process is unknown." (PMID 25801123, 2015). "Our mouse model clearly identifies EphB2 as an ependymoma oncogene and a requisite for cellular transformation; however, the mechanism underlying this function remains unknown." (PMID 25801123, 2015). "We propose that EphB2 mediated ependymoma development is a multifactorial process requiring microenvironment directed receptor activation, resulting in changes in the phosphorylation status of key regulatory proteins, maintenance of a stem-like state and cellular proliferation." (PMID 25801123, 2015). "Interestingly, when a similar number of the EphB2-driven mouse primary ependymoma tumor cells (tdNSCs) RGCH02 were intracranially implanted at our current site, we see a very different luminescence profile (RGCH02) and survival curve." (PMID 25801123, 2015). "Additional constraints on where and when ependymomas develop may be a function of changes in EphB2 and ephrin-B ligand expression levels and patterns during normal CNS development." (PMID 25801123, 2015). "Consequently, this difference may explain the inability of EphB2 overexpressing adult Ink4a/Arf(−/−) STeNSCs to develop into ependymoma when used in our implantation system." (PMID 25801123, 2015). "Importantly, they identified previously unknown potential ependymoma oncogenes, such as EPHB2, which is selectively amplified and overexpressed in the supratentorial subgroup of EP." (PMID 25008045, 2014). "A pioneering study analyzed the alterations of DNA copy number and revealed the EphB2 amplification and INK4A/ARF deletion in supratentorial ependymoma." (PMID 40943224, 2025).
ependymoma (continued). "Induction of EphB2 signaling in cerebral neural stem cells lacking the Ink4a/Arf locus led to the development of supratentorial ependymoma in mouse brain." (PMID 40943224, 2025). "In 2005, research identified the overexpression of ephrin-A3, ephrin-A4, EPHB2, EPHB3, and EPHB4 in ependymoma tumor cells, either from frozen or formalin-fixed tumor samples, but the clinical impact remains unclear." (PMID 38612645, 2024).
lung adenocarcinoma (7 papers, 2019 to 2025). A carcinoma that arises from the lung and is characterized by the presence of malignant glandular epithelial cells. "To confirm the pathological role of this E2F1/EPHB2 axis in lung cancer patients, we analyzed the expression of these genes in the TCGA lung adenocarcinoma cohort." (PMID 37980331, 2023).
bladder cancer (6 papers, 2013 to 2025). "Moreover, in vitro studies demonstrated that EphB2 inactivation promoted cell proliferation, motility, and invasion of bladder cancer, implying that EphB2 loss was involved in tumor metastasis and invasion of bladder cancer." (PMID 35223830, 2022). "Correlation of low EPHB2 expression with muscle invasion in bladder cancer suggests that EPHB2 may be a key regulator of bladder cancer invasion and progression." (PMID 37023088, 2023). "However, EphB2 inactivation promoted cell proliferation, motility, and invasion of bladder cancer." (PMID 35223830, 2022). "EphA2 is the key mediator of progranulin signaling in bladder cancer where progranulin did also modestly activate EGFR, EphA4 and EphB2." (PMID 36471440, 2022). "To elucidate the roles of EphB4 and EphB2 in TCC of the bladder, we examined the expression of EphB4 and EphB2 in normal and TCC surgical bladder specimens, and also in bladder cancer cell and immortalized normal urothelial cell lines." (PMID 25148033, 2014). "EphB2 expression was reported to be absent or decreased in bladder cancer tissues, compared to the normal bladder tissues." (PMID 35223830, 2022). "EphB4 expression is confirmed in bladder cancer cell lines including 5637 demonstrating strong EphB4 staining with little or no EphB2 protein expression by Western Blot and immunostaining." (PMID 25148033, 2014). "We found EphB4 is consistently over-expressed while EphB2 expression is predominantly absent in bladder cancer." (PMID 25148033, 2014).
cutaneous squamous cell carcinoma (6 papers, 2016 to 2024). "EphB2 promotes cutaneous squamous cell carcinoma (cSCC) cell proliferation via the Erk1/2 signaling pathway." (PMID 39532838, 2024). "Activation of EPHB2 promotes the progression of cutaneous squamous cell carcinoma cells by accelerating the production of invasive proteinases like MMP13 and MMP1." (PMID 32102656, 2020). "EphB2 is specifically overexpressed by cutaneous squamous cell carcinoma cells and promotes proliferation, migration, invasion, and growth of this tumour." (PMID 31065284, 2019). "EPHB2 is found to play a critical role in the progression from early-stage cutaneous squamous cell carcinoma to an advanced stage, and it is speculated to be a therapeutic target for invasive cutaneous squamous cell carcinoma." (PMID 36203528, 2022). "Furthermore, EphB2 plays a role in the progression of cutaneous squamous cell carcinoma." (PMID 31065284, 2019).
lung carcinoma (6 papers, 2020 to 2026). "The results indicated that the expression of COL5A2 and EPHB2 was obviously elevated in lung cancer tissue." (PMID 34419075, 2021). "The results showed that higher levels of COL5A2 and EPHB2 was correlated with worse survival status of lung cancer patients." (PMID 34419075, 2021). "The results showed that the expression levels of COL5A2 and EPHB2 were obviously upregulated in lung cancer tissue compared with normal tissue." (PMID 34419075, 2021). "They discovered EPHB2 maybe a key gene that are substantially expressed in lung cancer." (PMID 37377916, 2023). "Besides no record about SCN8A, THPA confirmed a similar tendency for an increased expression of HDAC1, DLG1, EPHB2 and CALB1, while GDNF was not apparently changed in either normal or lung cancer tissues; no data were available for SCN8A." (PMID 32102656, 2020).
pancreatic cancer (6 papers, 2014 to 2022). "EphB2 was reported to be highly expressed in pancreatic cancer tissues and associated with shortened survival." (PMID 35223830, 2022). "Silencing EphB2 accelerated pancreatic cancer growth by facilitating cell proliferation through triggering G1/S phase transition, indicating EphB2 forward signaling has a tumor suppressing function." (PMID 35223830, 2022). "Multivariate analyses showed that EphB2 was an independent prognostic factor in human pancreatic cancer." (PMID 35223830, 2022). "The expression of EphB2 in the human pancreatic cancer cell line, CFPAC‐1, was successfully suppressed by RNAi to elucidate the relationship between EphB2 and tumor formation." (PMID 33794069, 2021). "Our study showed that EphB2 highly expressed in the tissue of pancreatic cancer tumors, and QYHJ displayed a strong effect on the decrease of the expression of EphB2." (PMID 31147453, 2019). "Our previous study was designed to investigate this correlation by eliminating EphB2 expression using lentivirus-based RNAi to observe the biological characteristic changes in pancreatic cancer CFPAC-1 cells." (PMID 24959213, 2014). "Despite the clear link between EphB2 and a number of cancers, little is known concerning the correlation between EphB2 and pancreatic cancer prognosis." (PMID 24959213, 2014). "Furthermore, the high expression of EphB2 indicated a better response rate to Qingyihuaji formula (QYHJ) treatment in pancreatic cancer CFPAC-1 cells, but the contradictory results need more thorough research." (PMID 35223830, 2022). "However, another study reported that silencing EphB2 accelerated pancreatic cancer growth by promoting cell proliferation through triggering G1/S phase transition, which depended on a CyclinD1/CDK6 cell-cycle regulated signal." (PMID 35223830, 2022). "For example, EphB2-ephrin-B1 promoted the invasion of pancreatic cancer cells." (PMID 35223830, 2022). "EphB2-ephrin-B1 induces the invasiveness of pancreatic cancer cells." (PMID 34360867, 2021). "QYHJ could effectivly enhance the antihuman pancreatic tumor activity of GEM, which may be through inhibiting pancreatic cancer stem cell differentiation by lncRNA AB209630/miR-373/EphB2-NANOG signaling pathway." (PMID 31147453, 2019). "Furthermore, our previous study revealed that inhibition of EphB2 expression in pancreatic cancer CFPAC-1 cells resulted in the promotion of cancer growth by stimulating cell proliferation and decreasing apoptosis." (PMID 24959213, 2014). "Therefore, EphB2 may act as a predictive factor for QYHJ treatment in pancreatic cancer CFPAC-1 cells." (PMID 24959213, 2014). "Therefore, EphB2 acts as a tumor suppressor in pancreatic cancer." (PMID 24959213, 2014). "Therefore, EphB2 acts as a predictive factor for QYHJ treatment in pancreatic cancer CFPAC-1 cells." (PMID 24959213, 2014). "Accordingly, a higher expression of EphB2 acted as a positive predict factor for QYHJ treatment, with the exception of being a prognostic factor in pancreatic cancer; an additional experiment was performed to explore this mechanism." (PMID 24959213, 2014). "In addition, QYHJ showed an obvious effect against the gemcitabine (GEM) resistant pancreatic cancer, which probable by inhibiting cell migration, increasing the mRNA expression of lncRNA AB209630, and decreasing the mRNA levels of EphB2, miR-373, and NANOG." (PMID 35223830, 2022). "By acting as a positive prognostic factor in pancreatic cancer, or a distinctive predictive factor for QYHJ treatment, partially reveals the mechanism of the different responses to QYHJ treatment in cells that express different levels of EphB2." (PMID 24959213, 2014). "In conclusion, QYHJ exhibited a significant effect against the GEM resistance pancreatic cancer, which may be probably through the inhibition of cell migration, up-regulate the levels of lncRNA AB209630 and down-regulate the levels of miR-373, EphB2, and NANOG." (PMID 31147453, 2019).
pancreatic cancer (continued). "Similarly, EphB2 inhibition also reduced the apoptosis of CFPAC-1 cells by increasing Bcl-2 expression, with EphB2 acting as a tumor suppressor in the cell proliferation and apoptosis in pancreatic cancer." (PMID 24959213, 2014).
prostate tumors (6 papers, 2006 to 2022). "The notion of EPHB2 (which encodes the bi-directional ephrin receptor B2) as a MR of the BMI-associated adipose cell state is consistent with the literature that has linked EPHB2 expression to lipid metabolism in prostate tumor cells and adipose ephrin signaling to obesity in mice." (PMID 34793442, 2021).
head and neck squamous cell carcinoma (5 papers, 2020 to 2025). A squamous cell carcinoma that arises from any of the following anatomic sites: lip and oral cavity, nasal cavity, paranasal sinuses, pharynx, larynx, and salivary glands. "Ephrin type B receptor 2 (EPHB2) in small EVs derived from head and neck squamous cell carcinoma (HNSCC) activated ephrin-B reverse signaling and induced STAT3 phosphorylation in ECs, which promoted angiogenesis both in vitro and in vivo." (PMID 34966744, 2021). "Moreover, EVs from head and neck squamous cell carcinoma also exerted an effect, both in vitro and in vivo, in driving tumor angiogenesis through the ephrin type B receptor 2 (EPHB2)." (PMID 32384712, 2020). "EphB2 overexpression was detected in head and neck squamous cell carcinoma (HNSCC) patient and correlated with poor patient survival." (PMID 35223830, 2022). "For instance, EphB2 proteins carried by extracellular vesicles derived from head and neck squamous cell carcinoma (HNSCC) show pro-angiogenic effects, possibly by stimulating ephrin-B reverse signaling on neighboring endothelial cells." (PMID 34360867, 2021).
systemic lupus erythematosus (5 papers, 2013 to 2025). An autoimmune multi-organ disease typically associated with vasculopathy and autoantibody production. "Interestingly, we observed that patients with lupus positive for anti-EphB2 AAb had more often experienced cardiovascular events than patients negative for this AAb at the time of blood draw." (PMID 27617966, 2016). "EphB2 was expressed by human brain microvascular ECs, which was found as a target of autoantibody from a patient with ANE complicated with systemic lupus erythematosus (SLE)." (PMID 25873770, 2015). "Using SARF, we successfully identified ephrin type B receptor 2 (EphB2), which has critical functions in neuronal and endothelial cells (ECs), as a target of autoantibody from a patient with ANE complicated with systemic lupus erythematosus (SLE)." (PMID 24139226, 2013).
atherosclerosis (4 papers, 2020 to 2024). A disease characterized by the build-up of fatty material and calcium deposition in the arterial wall resulting in partial or complete occlusion of the arterial lumen. "EphB2 protein is involved in atherosclerosis, and EphB2 expression in atherosclerotic plaques increases with plaque severity." (PMID 39027720, 2024). "Validating the important role of LOC107986345/miR-128-3p/EPHB2 axis in the occurrence and development of atherosclerosis from another aspect." (PMID 35523945, 2022). "Based on this observation, an observed increase in EPHB2 expression upon monocyte‐to‐Mφ differentiation and combined with the fact that the EPHB2 gene is located on a myocardial infarction susceptibility locus, we hypothesized a role for monocytic EPHB2 in atherosclerosis development." (PMID 32337793, 2020). "In line with the limited amount of in vivo studies, to date also no clinical studies have been conducted on the potential therapeutic options of EPHB2 and its EphrinB ligands in inflammation, immunity, or atherosclerosis." (PMID 32337793, 2020). "Immunohistochemical staining of human aortic sections at different stages of atherosclerosis showed that EPHB2 and its ligand EphrinB are expressed in atherosclerotic plaques and that expression proportionally increases with plaque severity." (PMID 32337793, 2020). "We set out to assess the role for monocytic EPHB2 and its Ephrin ligands in human atherosclerosis and show a role for EPHB2 in monocyte functions independently of its EphrinB ligands." (PMID 32337793, 2020). "However, specific knockout of EPHB2 in the monocytic cell lineage would be an interesting way to further study the role of monocytic EPHB2 in atherosclerosis in vivo." (PMID 32337793, 2020). "Limited in vivo data on the role of EPHB2 in atherosclerosis is available." (PMID 32337793, 2020). "In addition, we showed increasing expression of both EPHB2 and EphrinB in progressing stages of atherosclerosis." (PMID 32337793, 2020). "Although the exact means by which Ephrins affect atherosclerosis development remains to be elucidated, we have shown that EPHB2 plays a role in atherosclerosis by mechanisms that are not related to the activation by trans nor cis interaction of the currently known EphrinB ligands." (PMID 32337793, 2020).
neuroblastoma (4 papers, 2015 to 2024). Neuroblastoma (NB) is the most common solid, extracranial childhood tumor. "FLAG-tagged EphB2 was expressed in the neuroblastoma cell line NG108, treated with either ephrin-B1 or control reagents, and immunoprecipitated." (PMID 28719605, 2017). "In a subsequent study, EPHB2 expression was demonstrated in low-stage neuroblastoma tumors, correlating with MYCN expression in tumors without MYCN amplifications." (PMID 38612645, 2024). "We first investigated whether neuroblastoma SK-N-SH cells and HEK293-tau express endogenous EphB2." (PMID 26119563, 2015).